BRCA2 (BRCA2 DNA repair associated)
Diseases named in the same sentence as BRCA2 in open-access papers (continued):
Sharing a sentence is not in itself a finding about the gene and the disease.
tumor (continued). "Of the 146 FFPE HGSC tumour specimens tested, 41 (28%) carried a Tier I/II variant in either BRCA1 or BRCA2 (n = 36), or BRCA1/2 plus a second variant (n = 5)." (PMID 36011309, 2022). "Highly mutated genes like BARD1, MALT1, BRCA1/BRCA2, EIF3K, PTEN, FGFR2, and MAP3K1 were also found to overlap with SVs of the tumor sample that were identified by one or more technologies in our study." (PMID 36514120, 2022). "PARP inhibitors impair SSB repair to cause tumor cells to transform into DNA DSBs in the S phase, which leads to cell death due to mitotic catastrophe or apoptosis in tumors with BRCA1 and BRCA2 mutations as well as an HR deficiency." (PMID 35480096, 2022). "HGSC is associated with lower prevalence but recurrent somatic mutations in NF1, BRCA1, BRCA2, RB1, and CDK12 in around 5–8% of tumours." (PMID 36531003, 2022). "Of particular relevance for its tumor suppressor role are evidences showing that BRCA2 can promote RCD through a mechanism conserved from yeast to mammals and specifically anoikis in human epithelial cells." (PMID 35734584, 2022). "Among the 247,926 tumors, we identified reversion mutations in 75 tumor samples: 32 with BRCA1 and 43 with BRCA2 reversion mutations." (PMID 36557020, 2022). "Tumor cells with defective BRCA1 or BRCA2 lack the ability to perform HR efficiently thus sensitizing BRCA-mutant tumors to PARP inhibitors." (PMID 35869047, 2022). "Four carriers of germline mutations had additional somatic DDR mutations in the primary tumor: ERCC4; BRCA1, ATM, FANCD2, and MLH1; BRCA1; and BRCA2, RAD50, and ATR." (PMID 36446793, 2022). "OncoKB and COSMIC database screening identified 36 tumour-related genes including BRCA2 and FANCD2 in all groups." (PMID 36686473, 2022). "In this context, it was reported that hereditary breast and ovarian cancer syndromes can be caused by loss-of-function germline mutations in one of two tumor-suppressor genes, BRCA1, and BRCA2." (PMID 36268271, 2022). "A report on the outcomes of 1211 men undergoing active surveillance, including 11 BRCA1, 11 BRCA2 and 5 ATM germline carriers, has shown that BRCA2 carriers are more likely to undergo a tumour grade re-classification in subsequent biopsies." (PMID 33106584, 2021). "Tumour BRCA1/BRCA2 testing in 116 Manchester cases identified 7 (6%) BRCA1 and 5 (4.3%) BRCA2 somatic PVs as well as 1 (0.9%) BRCA1 and 1 (0.9%) BRCA2 somatic VUS each." (PMID 34503154, 2021). "For the tumor suppressor BRCA2, two OB folds bind to ssDNA, and a third OB fold is involved in protein–protein interactions." (PMID 34639195, 2021). "There were six BRCA1/BRCA2 PVs that showed discordance between germline and tumour testing, five in the NELCN cases and one from the Manchester cases, comprising 10.3% of all germline PVs." (PMID 34503154, 2021). "Three tumours showed alterations in RAD51D, one of which showed a concomitant P/LP variant in BRCA2." (PMID 34680387, 2021). "In particular, BRCA2 exerts tumor-suppressing properties by mediating DNA double-strand break repair to prevent mutagenesis and eventual carcinogenesis." (PMID 33968986, 2021). "By mining for the potential impact of stop-gain mutant BRCA2-S871Ter, differentially expressed genes were obtained from RNA-seq data of patients’ tumor tissue and the GEO database GSE62564." (PMID 34367235, 2021). "Germline BRCA2-mutant prostatic tumors harbor various dysregulation of signaling pathways related to aggressive tumor biology, including amplification of the WNT pathway modulator MED12L." (PMID 34884926, 2021). "This study has some limitations, such as that the role of BRCA2 alteration in immunotherapy in specific tumor type warrants further study." (PMID 33961040, 2021). "Other mouse models have also revealed tumor predisposition upon tissue-specific inactivation of the RAD51 loading factors Palb2 and Brca2." (PMID 33923105, 2021).
tumor (continued). "The tumor suppressor BRCA2 is a key player in homologous recombination (HR), a major pathway for the repair of DNA double-strand breaks." (PMID 33919707, 2021). "We report here the discovery of CAM833, a sub-micromolar chemical inhibitor of the regulatory protein-protein interaction between the RAD51 recombinase and the BRC repeat motifs of the tumor suppressor BRCA2." (PMID 33662256, 2021). "The BRCA1 and BRCA2 genes play an important role in maintaining genomic integrity and tumor suppression through the mediation of DNA repair by homologous recombination and reactivation of replication." (PMID 33525353, 2021). "As tumor suppressor genes, mutations of BRCA1 (MIM 113705) and BRCA2 (MIM 600185) are closely related to the development of BC." (PMID 34926254, 2021). "The most common HR-disrupting mutations in tumor cells involving BRCA1 and BRCA2 are single-nucleotide mutations, short insertions or deletions that lead to frame-shifts." (PMID 34884434, 2021). "The tumor suppressor BRCA2 has a pivotal role in HR-mediated repair and in the protection of stalled replication forks, while its absence is accompanied by genome instability and chromosome breakage." (PMID 33888558, 2021). "Despite representing distinct tumour types, there has been limited success in identifying gene expression profiles related to BRCA1 and BRCA2 pathogenic variants in either tumour or normal tissue." (PMID 34287743, 2021). "The BRCA1 and BRCA2 proteins are described as tumor suppressors and have been found to play a significant role in DNA damage repair, specifically the repair of DNA double strand breaks (DSBs), which ensures chromosome structure maintenance." (PMID 34439109, 2021). "The fixed nature of the PIAS4 and NUMB lesions supports a model suggesting that these likely promoted the BRCA2 phenotype of this tumor." (PMID 34011996, 2021). "Of these, 11 (19%) patients had BRCA1/2-mutated tumors (7 BRCA1 and 4 BRCA2), 2 (4%) patients had tumors with BRIP1 mutations, and 1 (2%) patient had a tumor with a two-copy deletion of RAD51C." (PMID 34552099, 2021). "The pathogenic germline variants in mCRPC, recurrent germline and somatic variants, and hotspot positions in different tumour types were mapped onto ATM, BRCA1, BRCA2, and MUTYH available structures, in order to find 3D-clusters of variants." (PMID 34253785, 2021). "Although progress has been made in identifying functions for BRCA2 in DNA damage responses, much remains to be understood about the function of BRCA2 as a tumor suppressor." (PMID 34356050, 2021). "In this study, western blotting was performed to detect BRCA2 expression in the siblings’ tumor tissue." (PMID 34367235, 2021). "Real-time PCR was performed to confirm the relative expression of BRCA2 in the siblings’ tumor tissue." (PMID 34367235, 2021). "Of patients with pathogenic variants in BRCA2 or PALB2, 60% of AA patients (12/20) versus 12% of EA patients (3/25) presented with TNBC versus any other tumor subtype (P = 0.001)." (PMID 33479248, 2021). "The role of BRCA2 in DDR is relevant not only for tumor suppression, but also for organisms’ viability." (PMID 34504103, 2021). "VUS in these domains would seem less likely to affect BRCA2 functions related to its role as a tumor suppressor." (PMID 34356050, 2021). "It is essential that BRCA2 localizes to the nucleus to carry out its genome integrity and tumor suppressor functions, and thus, contains several putative nuclear localization signals (NLS)." (PMID 34065235, 2021).
tumor (continued). "The distinct tumor-immune microenvironments in BRCA1 and BRCA2-deficient tumors are modulated by distinct mutational and copy-number profiles, which can predispose to distinct immune checkpoint blockade response." (PMID 33540843, 2021). "The first tumor, PS13-9062, was a grade 3 ER+, PR+, and ERBB2- (pT2, pN0) arising in a patient with a germ line BRCA2 mutation." (PMID 34011996, 2021). "In line with this, pathogenic BRCA1, BRCA2 and PALB2 mutations contribute to distinct tumor inflammatory architecture." (PMID 34572943, 2021). "Numerous murine models of BRCA2 have been developed to investigate BRCA2 tumor suppressor function but have been met with difficulties due to the lethality of most of these models during embryogenesis." (PMID 34359565, 2021). "Further, understanding BRCA2 function as a tumor suppressor demands experiments that utilize mutants of full-length BRCA2 to determine how various domain-specific activities are integrated together." (PMID 34356050, 2021). "Durable remissions were associated with a high tumor mutation burden, evidence of DNA repair disruption (via BRCA2 mutations and EMSY overexpression), and tumor infiltration of PD‐L1 expressing immune cells." (PMID 33811746, 2021). "This implies that AURKB disruption leads to a decrease in cell proliferation and cytokinesis whereas disruption in BRCA1/BRCA2 resulted in abnormal cytokinesis, eventually, encouraging tumor progression." (PMID 33915740, 2021). "Representative graphs show the striking tumor regression of PDX 435.1A-Cx treated with talazoparib + carboplatin compared to the vehicle control, as expected given the loss of BRCA2." (PMID 34413304, 2021). "Molecular testing of tumor tissue identified an additional five and three patients with somatic BRCA1 and BRCA2 mutations, respectively." (PMID 33668244, 2021). "A total of 10 patients with a familiar predisposition for EOC and a known mutation in BRCA1, BRCA2 or RAD51C and available tumor tissue were included in the cohort." (PMID 33482905, 2021). "PALB2, the partner and localizer of BRCA2 and the bridge between BRCA1/2, located in 16p12.2, is a tumor-suppressor gene that encodes a protein essential for homologous recombination in collaboration with BRCA2 during DNA double-stranded break repair." (PMID 34298749, 2021). "Further and more in-depth studies are required to define the complementary functions of BRCA1 and PALB2/BRCA2 in tumor suppression." (PMID 33893322, 2021). "The potential to exploit this scenario became apparent when two independent studies reported dramatic cytotoxicity of PARP inhibitors in the context of deficiencies in the tumor suppressor genes BRCA1 and BRCA2 (breast cancer susceptibility genes 1 and 2)." (PMID 33888558, 2021). "Despite its well-established identity as a tumor suppressor, much remains to be understood about BRCA2." (PMID 34356050, 2021). "The tumour suppressor PALB2 mediates the physical interaction of BRCA2 with the COOH-terminal fragment of BRCA1." (PMID 34771713, 2021). "BRCA1 and BRCA2 are human tumor suppressor genes located on the long arm of chromosomes 17 and 13, respectively." (PMID 34198652, 2021). "The tumor-normal matched genomic analysis of the metastatic bone lesion and blood sample confirmed the presence of the known germline BRCA2 alteration (p.E260fs, c.778_779del, ClinVar variation ID 38119)." (PMID 33619265, 2021). "BRCA2 is a tumor suppressor with a clearly defined role in HRR, an error-free repair pathway, and a primary cellular mechanism for the repair of DSBs." (PMID 34283091, 2021). "BRCA1 and BRCA2 (loci 17q21 and 13q12.3, respectively) are major tumor-suppressor genes involved in DNA double-stranded break repair by homologous recombination (HRR)." (PMID 34298749, 2021).
tumor (continued). "BRCA2-deficient HCT-15 cells and BRCA-proficient RKO cells were subcutaneously injected into nude mice, and once tumor volume reached ~70 mm3, either simmiparib or LY2090314, alone or in combination, was injected every other day for 14 days." (PMID 33589588, 2021). "Immune infiltrates in BRCA2 mutant tumors assume a potent anti-tumor phenotype, whereas myeloid cells infiltrating BRCA1 mutant tumors show immunosuppressive capacity." (PMID 34572943, 2021). "The BRCA1 and BRCA2 genes mediate repair of DNA double strand breaks and thus are termed tumour suppressor genes." (PMID 34209669, 2021). "Among the target genes, BRCA2 was identified as a tumor-suppressor gene involved in DNA damage repair." (PMID 33968986, 2021). "Compared to control vehicle treatment, treatment with NSC617145 (25 mg/kg body weight) resulted in a marked decrease (p = 0.05) in BRCA2−/− tumor growth." (PMID 34772932, 2021). "The clinical phenotype correlates with the typical BRCA2 tumor characteristics with positive estrogen and progesterone receptors and negative Her2 status." (PMID 34456966, 2021). "The BRCA2 tumor suppressor protects genome integrity by promoting homologous recombination-based repair of DNA breaks, stability of stalled DNA replication forks and DNA damage-induced cell cycle checkpoints." (PMID 34645815, 2021). "The most frequently mutated genes in the tumor fragments of women were USH2A, ATM, and IGF2R; in female dogs, they were USH2A, BRCA2, and RRM2." (PMID 34680380, 2021). "The tumor suppressor BRCA2 protects stalled DNA replication forks from unrestrained degradation; however the mechanism whereby unprotected stalled forks are preserved and restarted has remained elusive." (PMID 34772932, 2021). "BRCA2 protein was expressed at lower levels in monoallelic and biallelic mutant tumor cell lines than in wild-type cell lines." (PMID 32980867, 2020). "Similar results were obtained in two other BRCA2 monoallelic and biallelic mutant tumor xenograft models (p < 0.01), and significantly improved survival rates for the MMC-treated mice compared with the control mice (p < 0.01)." (PMID 32980867, 2020). "In terms of failure patterns, many studies have compared ipsilateral and/or contralateral tumor recurrence in BRCA1 and BRCA2 mutation carriers and patients with sporadic cancers." (PMID 33019612, 2020). "BRCA1 and BRCA2 are tumor-suppressor genes that code for proteins involved in homologous recombination (HR) repair." (PMID 33302444, 2020). "RNA tumor profiling demonstrated that BRCA2 tumors are mainly of the luminal B subtype and are more likely than non-BRCA2 tumors to be ER-positive and of high grade, with pushing margins." (PMID 32481735, 2020). "Of note, several genes involved in the HRR pathway, including BRCA2 and RAD51, play a role in tumor development and are implicated in HR deficiency when mutated or defective." (PMID 33324554, 2020). "Transcripts coding for tumor-suppressing proteins (Apc, Brca2, and Cdc73) are upregulated while tumor-promoting protein transcripts are downregulated (Met, Junb, and Pim1)." (PMID 32970688, 2020). "In summary, we find that ER-positive tumours have a poor long-term prognosis in BRCA2 carriers, but blocking exposure to female hormones in the form of bilateral oophorectomy or endocrine therapy appears to mitigate this effect." (PMID 32939053, 2020). "The survival analysis revealed PEG3 mutant patients had worse survival outcome after controlled for multiple factors including age, tumor stage and mutations of BRCA1, BRCA2 and POLE." (PMID 32729618, 2020). "These experiments showed that treatment of mice with AG14361 caused a complete regression of the BRCA2 mutant tumour but growth of the BRCA2 corrected tumour was unaffected." (PMID 32121331, 2020). "BRCA1 carriers were largely (74%) basal-like, while tumours from BRCA2 carriers and BRCAx were largely (73% and 60%) luminal, an observation which has also been observed in subsequent studies." (PMID 33081408, 2020).
tumor (continued). "High throughput sequencing methods, such as Tumor Mutation Burden, somatic detection of BRCA1 and BRCA2 single nucleotide variants and copy number variations that can address patient to targeted therapeutic approaches, are strongly influenced by DNA integrity." (PMID 32140450, 2020). "Metastatic tumor samples from the liver contained 30 additional pathogenic mutations, including additional mutations in BRCA1 and BRCA2." (PMID 33198737, 2020). "BRCA2 is a tumor suppressor that plays a major role in DNA repair pathways and has been found recently in the protection of replication forks." (PMID 33043007, 2020). "PARP‐inhibitors are the first class of MTA that targets mutations in tumor suppressor genes (BRCA1 and BRCA2)." (PMID 32881420, 2020). "The BRCA1 and BRCA2 tumour suppressor genes play an important role in DNA damage repair to prevent the development of tumours." (PMID 32328196, 2020). "PDX HBCx-118 (BRCA2 and AKT1 mutated) responded to the combination of AZD5363 plus fulvestrant, while PDX HBCx-142 (AKT1 and mTOR mutated) responded with tumour regression to everolimus and with stable disease to volasertib, AZD5363 and palbo + fulvestrant." (PMID 32792481, 2020). "Regarding the mutator phenotype, we identified BRCA2 and NEIL3 to be associated with higher mutational burden (i.e., 20 mutations/tumor) in tumors in Caucasians." (PMID 32300177, 2020). "As BRCA1, also BRCA2 plays an important role in tumor suppression and DNA repair process, probably for its direct interactions with Rad51 during homologous recombination in two different domains: the eight BRC repeat and DBD domain." (PMID 32438681, 2020). "Cell viability data demonstrated that olaparib, MMC and melphalan significantly decreased the viability of BRCA2 monoallelic and biallelic mutant gastrointestinal tumor cells at a concentration of 10 μM compared with that of BRCA2 wild-type tumor cells." (PMID 32980867, 2020). "Exploitation of the synthetic lethal relationship between defects in BRCA1 and BRCA2 tumour suppressors and with RAD52 depletion or inhibition has opened many new questions into the role of the RAD52 protein in genome maintenance." (PMID 31799622, 2020). "As an autosomal dominant tumor suppressor gene, the gene of BRCA2 or BRCA1 contribute to the repair of DNA." (PMID 32571290, 2020). "Next, we tested the in vivo efficacy of MMC in three BRCA2 monoallelic and biallelic mutant tumor xenograft models." (PMID 32980867, 2020). "LOH was evaluated in patients with BRCA1 or BRCA2 germline pathogenic variants (n = 11 for BRCA1; n = 6 for BRCA2) and VUS (n = 1 for BRCA1; n = 7 for BRCA2) in the tumor samples." (PMID 32850417, 2020). "Studies have identified CNKN1A as a target gene of YY1 that binds to the BRCA2 protein to have a role in tumor suppression." (PMID 33232269, 2020). "BRCA2 along with BRCA1 are well-known tumor suppressors and thus typically deleted or functionally deficient in tumors." (PMID 33043007, 2020). "In patients with germline BRCA2 VUS, loss of the wild type allele was seen in 29% (2/7) of the tumor samples." (PMID 32850417, 2020). "The importance of this domain in the overall function of gene, as a tumor suppressor, is due to the binding of BRCA2 protein with Rad51 and their role in homologous recombination process." (PMID 32438681, 2020).